HAVCR2 (hepatitis A virus cellular receptor 2)
Diseases named in the same sentence as HAVCR2 in open-access papers (continued):
Sharing a sentence is not in itself a finding about the gene and the disease.
tumor (continued). "Tregs expressed higher levels of inhibitory markers, such as HAVCR2/TIM3 and TIGIT in PT and tumour‐invaded TDLN." (PMID 37491740, 2023). "The infiltration of CD4 and CD8 T cells, as well as the levels of the TEX marker genes (HAVCR2, TIGIT, CTLA4, LAG3, and PD1) and tumor stem cell marker genes (CD44 and PROM1), were all greater in tissue samples with high TEXSRGs-score." (PMID 37957420, 2023). "In THCA tumor, CTLA4 (rho = 0.691), HAVCR2 (rho = 0.610), TIGIT (rho = 0.641), VTCN1 (rho = 0.618) showed remarkably positive with FAP expression." (PMID 37166418, 2023). "We further analyzed the tumor microenvironment between different RiskScore groups, and it was also apparent that the expression of PDCD1, CD274, CTLA-4, HAVCR2 and LAG3 in the low-RiskScore group was relatively high." (PMID 37154982, 2023). "The major immune checkpoints include PDCD-1, CD274 (also known as PD-L1), CTLA-4, HAVCR2 (also called TIM-3), LAG-3 and TIGIT which are responsible for tumor immune escape." (PMID 37810780, 2023). "Previous have demonstrated that tissue resident CXCR6+ CD8 T cells are important components of tumor-infiltrating lymphocytes, which further evolve into GZMK+HAVCR2- subsets and terminally differentiated T cells." (PMID 37593098, 2023). "To investigate the immune profiles of c-Scorehi tumors across the 25 TCGA tumor types, we evaluated immunomodulatory genes involved in immune checkpoint blockade response, (CD274 [PD-L1], PDCD1 [PD-1], HAVCR2 [TIM3], LAG3, TIGIT, CTLA4, and FASLG)." (PMID 37558751, 2023). "SIGLEC15, PDCD1LG2 (PD-L2), TIGIT, PDCD1 (PD-1), HAVCR2 (TIM3), CTLA4, LAG3, and CD274 (PD-L1) are transcripts related to immunological checkpoints that have a function in tumor immune evasion." (PMID 36042287, 2022). "In the TCGA dataset, the expression levels of CD2, HAVCR2, HLA-C, HLA-DRA, HLA-E, KLRK1, and TYROBP were all significantly downregulated in tumor tissues compared with para-tumor tissues." (PMID 35794593, 2022). "TIM-3 protein is a type I membrane protein also known as hepatitis A virus cell receptor 2 (HAVCR2), which is a negative regulator of anti-tumor immunity." (PMID 36741400, 2022). "Correlation analysis of six prognostic MDGs (ABCG1, KDF1, KITLG, TGFA, HAVCR2, and CD14) and six types of immune infiltrating cells, including tumor purity, B cells, CD8+T cells, CD4+T cells, macrophages, neutrophils, and dendritic cells was performed." (PMID 35774505, 2022). "HAVCR2, namely, TIM-3, which inhibits tumor immunity with depletion of T cells, is a negative regulator of immune check points." (PMID 35350786, 2022). "The results showed that CTLA4, HAVCR2, PDCD1, PDCD1LG2, and TIGIT significantly differed in tumor tissues and normal tissues." (PMID 36618928, 2022). "The results showed that CD68 expression positively correlated with the expression of LAIR1, HAVCR2, LGALS9, and PD-1 (PDCD1) in most of the 33 tumor types." (PMID 35550532, 2022). "Immune checkpoint molecules, such as PD-1, PD-L1, HAVCR2, LAG3, and CTLA-4, play an important role in tumor immune evasion." (PMID 36186792, 2022). "And the expression of HAVCR2, CCR7 and CD28 had poor correlation with the clinicopathological features of PCa in age, GS and tumor stage." (PMID 36505767, 2022). "The immune-checkpoint genes PD-L1 (CD247), CTLA4, LAG3, TIM3 (HAVCR2) and IDO1 were assessed using gene expression data, with significantly higher expression of each in DDIR-positive tumours." (PMID 34728791, 2022). "The T-cell immunoglobulin and mucin domain 3 (TIM-3), also known as HAVCR2, has been proved to express in activated Th1 cells, Tregs, macrophages, dendritic cells, NK cells, and tumor cells." (PMID 36405712, 2022). "Intriguingly, CAFap presented significantly more interactions with tumor-infiltrating T-cell clusters than CAFmyo (p = 0.002), with a similar interactive pattern as that of TAM (e.g., LGALS9_HAVCR2/SORL1/CD47)." (PMID 36333338, 2022).
tumor (continued). "We found that CSF-1R was significantly correlated with tumor-related immunosuppressive molecules including PDCD1, CTLA4, CD80, CD86, HAVCR2, etc.." (PMID 35444953, 2022). "CTLA4, HAVCR2, PVRL2, PDCD1, SIGLEC15, TIGIT, and VTCN1 expression levels were higher in tumor tissues, while CD244, LAG3, PDCD1LG2, and CD274 expression levels were found to be lower." (PMID 35923695, 2022). "Tumor-infiltrating T cells significantly upregulated well-established co-stimulatory and inhibitory receptors TNFRSF9 (CD137, 4-1BB) and HAVCR2 (TIM-3)." (PMID 35874727, 2022). "To study how the HAVCR2 gene functions biologically, we explored the pathways of HAVCR2 using GSEA in 39 tumor types from TCGA." (PMID 36081997, 2022). "Previous studies have shown that infiltration of multiple immune cells, activation of CD274 (PD-L1), LAG3 and HAVCR2(TIM-3) and high immune scores played a crucial role in hot tumor." (PMID 35860239, 2022). "Meanwhile, we show the IHC staining of NRP1, HAVCR2, HHLA2CD44, TNFRSF18, TNFSF14, TNFRSF8, and CD276 in tumor tissues and normal tissues." (PMID 35685438, 2022). "Relative to the primary tumour, even-higher levels of three checkpoints—LAG3, TIGIT and HAVCR2—were expressed on MANA-specific TIL in the metastasis." (PMID 34290408, 2021). "Each CD44+ cell-type functions immunosuppression through different ways: CD44+ tumor cells express CD276, IL13, VEGFA, and IDO1; CD44+ TAMs express IL10, TGFB1, VEGFA, and HAVCR2; CD44+ T cells express CD274, TGFB1, CTLA4, LAG3, and PDCD1." (PMID 35187044, 2021). "HAVCR2/TIM-3 and PDCD1 were not only increased with disease progression, but also displayed consistent levels of elevation in MF lesions (plaque and/or tumor) when compared to different controls." (PMID 34204115, 2021). "Exhausted (terminal differentiation) CD8+ T cells (cluster 10 in Paratumor and cluster 0 in Tumor) were enriched with exhaustion genes CTLA4, PDCD1 and HAVCR2." (PMID 33429363, 2021). "We found that the exhausted CD8+ T cells located in the core of the tumor had a higher expression of immune checkpoint molecules, including PDCD1, CTLA4, LAG3, TNFRSF9/CD137, CD27, and HAVCR2." (PMID 34513820, 2021). "NK–tumor interactions included HLA-C/KIR2DL4, HLA-E/CD94 (KLD1), TIM3 (HAVCR2)/Galectin-9, CD96-PVR/Nectin1 and TIGIT-PVR/Nectin2." (PMID 33671917, 2021). "The expression of certain immune checkpoints (such as PDCD1LG2, HAVCR2, CD276, and IDO1) also played an important role in the regulation of immune response by inhibiting the activation of anti-tumor immunocytes and inducing immune escape." (PMID 34490033, 2021). "Eight tumor-related immunosuppressive molecules, CD274, CTLA4, HAVCR2, LAG3, PDCD1 (PD1), PDCD1LG2, SIGLEC15, and TIGIT, had higher expression in HNSCC tumor tissues compared with HNSCC normal tissues." (PMID 34917682, 2021). "For example, CD4+ naive T cells (cluster 0/cluster 2) located at the core of the tumor expressed more immune checkpoint molecules, such as CTLA4, LAG3, HAVCR2, and TNFRSF9/CD137." (PMID 34513820, 2021). "High expression of exhausted T-cell marker genes supported by established studies, including CXCL13, HAVCR2, and PDCD1, was concentrated in tumor tissue in single-cell transcriptional profiles." (PMID 34434188, 2021). "SUV39H1 overexpression significantly up-regulated the methylation level of HAVCR2 and LGALS9 in tumor tissues." (PMID 32699524, 2020). "In addition to the expression of CTLA-4 and PDCD1, tumor-infiltrating lymphocytes (TILs) express a number of other co-inhibitory receptors, including HAVCR2 and TIGIT, providing additional targets that could be exploited for inducing anti-tumor immune responses." (PMID 33585210, 2020). "As expected, the expression level of HAVCR2, CD40, SIGLEC7, CD86 genes are inversely correlated with tumor purity." (PMID 32021566, 2020). "TIM3 (HAVCR2) is an inhibitory receptor expressed on T cell and tumor cell surfaces which regulates Th1 and cytotoxic T cell responses." (PMID 31783776, 2019).
tumor (continued). "Intriguingly, tumor-reactive markers (CD39 and CD103) and exhaustion markers (PDCD1, LAYN, and HAVCR2) were specifically demethylated." (PMID 31892342, 2019). "Given HAVCR2 upregulation in FDIM, TIM-3 inhibition may improve immune-mediated tumour control in this disease." (PMID 40683913, 2025). "Tumor-infiltrating effector CD8 T cells were identified as drivers of LAG3, TNFSF9, and HAVCR2 overexpression, which suggests effector CD8 TILs are activated and exhausted relative to circulating leukocytes, a finding that is consistent with reports across multiple human tumor types." (PMID 39932553, 2025). "Then, DNMT3A binds to promoters of HAVCR2 and LGALS9 genes, increasing the methylation levels in these promoters and decreasing the expression of Tim-3 and Galectin-9 in SiHa and HeLa CC cells, as well as in vivo tumor growth." (PMID 41226543, 2025). "There was concurrent and significantly increased expression of the immune checkpoint pathway markers HAVCR2 (TIM-3), CTLA-4, PDCD1 (PD-1), PDCD1LG2 (PD-L1), LAG3, and TIGIT, demonstrating increased immune suppressive signaling from both the tumor and immune cell populations." (PMID 38418892, 2025). "In our study, we found that high PSMB2 expression may induce the upregulation of CD274, CTLA4, HAVCR2, LAG3, PDCD1, PDCD1LG2 and SIGLEC15, which are molecules on immune cells that facilitate tumor immune escape." (PMID 38467767, 2024). "Therefore, APOC1+ TAMs and CXCL11+ TAMs potentially suppress anti-tumor immunity by inducing T cell dysfunction, exhaustion or even apoptosis through LGALS9 − HAVCR2 pair." (PMID 39232806, 2024). "When assessing tumor-infiltrating exhausted CD8+ T cells with exhaustion unique gene markers, such as Lag3, Tigit, Havcr2, Ctla4, and Pdcd1, we observed that the Lag3 and Tigit levels in the MnBuOE/RT group were significantly lower than those in the other groups (p < 0.05)." (PMID 38671924, 2024). "Additionally, anti-PD1 combined with anti-HAVCR2, CTLA4, or TIGIT has been recently found to more effectively improve T-cell function, overcome resistance to anti-PD1 therapy, and eliminate tumour cells." (PMID 38297380, 2024). "We found several molecules that are significant in tumor initiation and treatment by immune checkpoint analysis, such as lymphocyte-activation gene 3 (LAG3), PTPRC, HAVCR2, B2M, LDHA, and LDHB, which may be used as a reference for tumor immunotherapy." (PMID 39014082, 2024). "These included a major Prf1highGzmhighPdcd1+Havcr2+ cluster resembling “exhausted” T (TEX) cells and a Pdcd1+Tcf7+Slamf6+ cluster resembling “stem-like” T cells, that were predominantly tumour-resident and expanded with anti-PD-L1." (PMID 38267413, 2024). "Interestingly, we observed marked upregulation of a series of immune checkpoints (e.g., CD86, CD80, HAVCR2 and LGALS9) in most tumor infiltrating myeloid cells, and a unique pattern in TAMs (e.g., NECTIN2, TNFRSF14, CD276 and TNFRSF9)." (PMID 38414027, 2024). "As the marker of exhaustive CD8 T cells, HAVCR2 regulates EMT by crosstalking Akt/GSK-3β/Snail signaling pathway with SMAD7/SMAD2/ SNAIL1 Axis, implicating the dual role of Community 1-related immune genes in EMT and tumor immune." (PMID 38331768, 2024). "HAVCR2 was reported to be involved in the process of ICIs re-initiating the tumor antigen-activating effector CD8+ T cells, lacking of which would cause the failed response to ICIs in patients." (PMID 38977778, 2024). "Furthermore, tumor-infiltrated CD8+ T and CD4+ T cells in the allografts highly expressed the activation/exhaustion markers, such as GZMB, GZMK, PDCD1, LAG3, HAVCR2, and CTLA-4." (PMID 37980406, 2023). "Analysis of RNA from CD45+ tumor infiltrating cells isolated from Kin1-WT and Kin1-NULL tumors was carried out which showed a reduction of various T cell inhibitory checkpoint pathway related genes, including Cd274, Vsir and Havcr2 in Kin1-NULL tumors." (PMID 36883731, 2023).
tumor (continued). "Additionally, a strong correlation between RHBDF2 upregulation and immune checkpoint genes (PDCD1, CD274, LAG3, CTLA4, TIGIT, HAVCR2) was observed in HCC, and these immune checkpoint genes can contribute to tumor immune escape and promote tumor progression." (PMID 36943228, 2023). "Furthermore, CTLA4 and LAG3 were negatively expressed in tumor-infiltrating lymphocytes, while CD96 and HAVCR2 were highly expressed in cluster CD8_1, indicating functional exhaustion of cells in this cluster within TME." (PMID 37533434, 2023). "HAVCR2 (Tim-3) has been shown to be expressed in the TME of NSCLC and affect T cell activation and can be used as a potential modulator of cancer immunotherapy to enhance the anti-tumor effect of checkpoint inhibitors." (PMID 36308553, 2023). "In the process of APOBEC mutagenesis, the increased expression of important immune checkpoint molecules, including PDCD1, TIGIT, HAVCR2, LAG3 and IDO1, and the elevated CYT score, which serves as cytotoxic effects and anti-tumor response, were highly suggestive of better immunotherapy response." (PMID 37215984, 2023). "In addition, ETO improves the therapeutic effect of TIM-3 (hepatitis A virus cellular receptor 2) monoclonal antibody in a tumor-bearing mouse model, further enhancing the CD8+ T cell-mediated anti-tumor immune response." (PMID 37554324, 2023). "In contrast, we did not see the differential expression of LAG3, PDCD1, and HAVCR2 genes in the blood of any patient groups, suggesting differences between the tumor and blood circulation immune microenvironments." (PMID 37762493, 2023). "Otherwise, the mRNA expression of LAG3, CTLA4, PD-1, PD-L1, and HAVCR2, tightly related to tumor immunosuppression or tolerance, were not significant differences in ACC with CENPFhigh, compared with CENPFlow (all p > 0.05)." (PMID 35123514, 2022). "The upregulation of PDL1, PDL2, HAVCR2, and TIGIT could be in an immunosuppressive status, thus facilitating tumor progression." (PMID 36698888, 2022). "The results found that the expression levels of ABCG1, HAVCR2, CD14, and TGFA were significantly increased (p < 0.05) in tumor tissue samples compared with para-cancerous control tissue samples, while the expression levels of KDF1 and KITLG were significantly decreased (p < 0.05)." (PMID 35774505, 2022). "Notably, CCL14 expression in HCC negatively correlated with PD-1, HAVCR2, and CTLA-4, suggesting its role in regulating tumor immunity." (PMID 36159990, 2022). "HAVCR2 expression exerted a pleiotropic effect on malignancy not only regulating immune infiltration but also involving DNA methylation, tumor biology, and metabolism." (PMID 36081997, 2022). "Notably, in the tumor tissues, we found that only the cells in VEGFA_MACRO interacted with those in TIGIT_CD8 via LGALS9/HAVCR2." (PMID 36531216, 2022). "Furthermore, we found that CSF-1R was significantly correlated with tumor-related immunosuppressive molecules (including PDCD1, CTLA4, CD80, CD86, HAVCR2)." (PMID 35444953, 2022). "Consistent with the gene expression profile of tumor antigen-specific CD8+ T lymphocytes in human tumors, the majority of all CD8+ subsets displayed an exhausted profile with expression of Tox, Pdcd1, CTLA4, Lag3, and Havcr2." (PMID 35260537, 2022). "In addition to the classical immune checkpoint molecules PD-1 and CTLA-4, T cell immunoglobulin mucin receptor 3 (TIM3, or HAVCR2) and LAG-3 are also included in the field of tumor immunotherapy research." (PMID 35601491, 2022). "Furthermore, TIGIT, LAG-3, HAVCR2 (TIM-3), and IDO1 are known as novel immune checkpoint targets that can suppress the activation of effector T lymphocytes, hence mediating a tumor immune escape mechanism." (PMID 35416526, 2022). "Subclusters with Entpd1 expression were assigned as tumor-specific T cells, including Treg (CD4+Foxp3+), CD8+ effector (Gzmb+Prf1+Ifng+), CD8+ effector memory (Cd44+Cd69+), CD8+ exhausted subclusters (Pdcd1+Lag3+Tigit+Havcr2+)." (PMID 36209176, 2022).
tumor (continued). "To comprehensively inspect the immune microenvironment of HCC TME, we firstly compared gene expression of immune inhibitory checkpoint molecules between tumor tissues and normal (peri-tumor) tissues, including CD274, CTLA4, HAVCR2, LAG3, PDCD1, PDCD1LG2, TIGIT, and SIGLEC15." (PMID 35444645, 2022). "In addition, immune checkpoints including PD-L1, HAVCR2, TIGIT, and LAG3 in the high-risk group were also higher than those in the low-risk group, which indicated that patients in the high-risk group might belong to the “hot” tumor that was tended to benefit from immune checkpoint inhibitor therapy." (PMID 35027921, 2021). "These genes were defined as the tumor reactive signature (TRS), including co-inhibitory receptors (CTLA4, PDCD1, TIGIT and HAVCR2), reactive markers (CD38 and ENTPD1), effector molecules (NKG7 and PRF1), tumor necrosis factor TNFRSF9 and critical exhaustion-related regulator TOX." (PMID 34804045, 2021). "We found different tumor purities, immune scores, stromal scores, fractions of different immune cells, expression of several HLA genes and expression of five immune checkpoint molecules (CTLA4, CD274, HAVCR2, LAG3 and TIGHT) among UCEC subtypes." (PMID 34368124, 2021). "CD8+ T cells in the HNSCC TME interactome, particularly with macrophages, are based on predicted CD274–PDCD1, HAVCR2–LGALS9, and TIGIT–NECTIN2 interactions that may dictate tumor rejection." (PMID 34921143, 2021). "Therefore, we evaluated the relationship between the expression of immune inhibitory molecules (TIGIT, PDCD1LG2, PDCD1, LAG3, HAVCR2, CTLA4, and CD274) in the immune ignorant, immune inactive, and hot tumor subtypes." (PMID 33777927, 2021). "CD4+ naive T cells (cluster 0 and cluster 2) at the core of the tumor express more immune checkpoint molecules, such as CTLA4, which has been used in clinical practice, and LAG3, HAVCR2, and TNFRSF9/CD137, which are currently undergoing clinical trials than those at other locations." (PMID 34513820, 2021). "However, immune checkpoint genes including IDO1, HAVCR2, PDCD1LG2, CD274, CTLA4, and TIGIT were significantly up-regulated in tumor samples (fold change >1.30, FDR q ≤ 1.0e-5)." (PMID 33257699, 2020). "HAVCR2, also known as TIM-3, was mainly distributed in NK cells and macrophages in NSCLC, which could suppress anti-tumor immunity." (PMID 32699529, 2020). "Tumour transcriptional analysis demonstrated that, as a rapid and early consequence of vaccination, several profoundly immunosuppressive genes were highly upregulated, including CD274 (PD-L1), LGALS9 (Galectin-9), TGFβ1, LAG3 and HAVCR2 (TIM-3)." (PMID 26861383, 2016). "Following coculture with E0771-Her2 tumor cells, A1R CAR T cells exhibited significantly increased production of IFNγ and TNF and increased expression of effector related genes PD-1 (Pdcd1), TIM-3 (Havcr2), Gzmb and Irf4 compared to control and A3R CAR T cells." (PMID 40610421, 2025). "While anti-tumor T cell subsets, such as T_C1_Cytotoxic cells, were enriched in the low-PCD group, the high-PCD group exhibited a significant accumulation of exhausted T cells, characterized by the expression of exhaustion markers such as LAG3, HAVCR2, CTLA4, TIGIT, and CXCL13." (PMID 40740783, 2025). "Key tumour–non-cancerous cell interactions include the PD-L1/PD-1 (CD274/PDCD1) and Galectin-9/TIM-3 (LGALS9/HAVCR2) pathways, which are significantly upregulated in Low TPS and show a negative correlation with TPS, indicating the influence of the tumour microenvironment (TME)." (PMID 39457550, 2024). "We found that in HNSCC, FAP expression is significantly correlated with CTLA4, HAVCR2, and CD276, suggesting that FAP may play a key role in regulating immune evasion and tumor immune suppression, but further exploration is needed to elucidate the specific mechanisms." (PMID 38826849, 2024).